BDNF (brain derived neurotrophic factor)
Diseases named in the same sentence as BDNF in open-access papers (continued):
Sharing a sentence is not in itself a finding about the gene and the disease.
Anxiety (continued). "In FM rats, reduced anxiety was associated with increased hippocampal expression of BDNF and COMT genes with a simultaneous increase in DAT gene expression." (PMID 36498900, 2022). "The physiological pathways of anxiety associated with the expression of BDNF, HTR2C, MAOA, and RGS2 can be affected by miR-22 and the repetitive behavior in heterozygous knocked-out mice can be prompted by the partial loss of miR-137." (PMID 36344488, 2022). "Associations with stress-related mood disorders and anxiety have been also reported in humans assessing BDNF methylation in peripheral tissues, such as blood and saliva." (PMID 35911240, 2022). "The goals of this study were (a) to assess the association between pandemic-related stress and postnatal anxiety and (b) to investigate the potential role of maternal BDNF methylation as a significant mediator of this association." (PMID 35911240, 2022). "The results exhibited a loss of the Smpd3 gene modulates anxiety behavior and stress responses, as well as the recovery of brain-derived neurotrophic factor (BDNF) expression, through exosomal miRNA in the hippocampus." (PMID 35163475, 2022). "The Pearson’s bivariate correlation indexes reported are significant, but the strength of the association of BDNF CpG-specific% methylation with pandemic-related stress and anxiety symptoms is mild." (PMID 35911240, 2022). "This study displayed BDNF Val66Met genotype was associated with anxiety trait in PD patients, in line with a previous study." (PMID 35815047, 2022). "In the present study, the ameliorated anxiety of stressed FMs was associated with an increased hippocampal concentration of BDNF mRNA." (PMID 36498900, 2022). "And haplotype for the three SNPs (rs6265-rs16917204- rs56164415) in gene BDNF should be taken into consideration to explore BDNF gene polymorphism and anxiety trait." (PMID 35815047, 2022). "Our recent research shows that in mice with anxiety caused by mutations in the brain-derived neurotrophic factor (BDNF) gene, music therapy reversed anxiety symptoms and increased BDNF mRNA and protein levels in several brain regions." (PMID 35586054, 2022). "In summary, we first explored the relationship among BDNF Val66Met polymorphism, plasma BDNF level and anxiety trait in PD patients." (PMID 35815047, 2022). "This SNP within the gene encoding for BDNF has been previously associated with other psychiatric disorders such as schizophrenia, anxiety, and depression; and, it has been linked with impaired neurocognitive function in healthy adults." (PMID 35625351, 2022). "Till now, the relationship between BDNF Val66Met polymorphism and anxiety-related traits in PD patients has been rarely explored." (PMID 35815047, 2022). "Clinical studies have shown that stress-related mental disorders, including anxiety, are associated with decreased levels of BDNF and its receptor TrkB in the brain." (PMID 36545308, 2022). "The hippocampus and cortex of germ-free mice were found to have lower levels of BDNF expression, and it was discovered that lower levels of BDNF expression were specifically linked to higher levels of anxiety and progressive cognitive dysfunction." (PMID 36248189, 2022). "Based on these findings, we proposed that stress-induced anxiety reduction is associated with the elevation of BDNF gene expression directly." (PMID 36012411, 2022). "In SM rats, increased anxiety was associated with reduced BDNF gene expression and increased MAO-A and MAO-B gene expression in the hippocampus." (PMID 36498900, 2022). "Mice deficient in BDNF show altered development of the GI tract innervations and reduced expression of BDNF was found to be specifically associated with increased anxiety and progressive cognitive dysfunction." (PMID 33946488, 2021). "While further work is required, our identification of this sex-specific association between maternal anxiety and maternal serum BDNF provides a highly novel example of the influence of fetal sex on the maternal state." (PMID 33462179, 2021).
Anxiety (continued). "In summary, we have discovered a sex-specific association between maternally reported symptoms of anxiety and elevated maternal serum BDNF at term, specifically in pregnancies with male infants." (PMID 33462179, 2021). "Recently, other genome-wide association studies have identified BDNF associations with several behavioral and cognitive attributes, such as “worry”/anxiety." (PMID 34760029, 2021). "Recent studies have also associated BDNF with behavior similar to that elicited by anti-anxiety drugs and antidepressants." (PMID 34884465, 2021). "A deficiency in BDNF in the neural circuits of the central amygdala (CeA) and medial amygdala (MeA) limits alcohol intake in rats and induces anxiety behaviors derived from BDNF deficiency." (PMID 33919862, 2021). "Brain-derived neurotrophic factor (BDNF) Val66Met polymorphism was significantly correlated with anxiety in patients with advanced gastric cancer." (PMID 34284736, 2021). "Exercise is also a well-known inducer of brain-derived neurotrophic growth factor (BDNF), which appears to be decreased in patients with anxiety disorders and increasing levels have been linked to reduced anxiety in rodents following exercise." (PMID 34566716, 2021). "Elevated serum pro‐inflammatory cytokines and cortisol levels, and reduced brain‐derived neurotrophic factor (BDNF) have been associated with anxiety." (PMID 34213086, 2021). "In the multiple regression analysis, only RA patients with anxiety (p = 0.002) and receiving biologics (p = 0.020) were significantly associated with lower serum levels of BDNF." (PMID 33673283, 2021). "Most studies have shown that decreased anxiety levels were caused by increased BDNF levels in the hippocampus region." (PMID 33110362, 2020). "Increased anxiety-related behaviors, decreased ventromedial prefrontal cortex volume and memory deficits have been observed in mice with BDNF Val66Met polymorphism." (PMID 33076878, 2020). "Previous studies have shown that stress exposure can lead to anxiety-associated phenotypes in rodents, which is consistent with the upregulation of BDNF in the amygdala." (PMID 32085670, 2020). "A reduction of ERK44/42 phosphorylation, linked to a reduction of BDNF levels, in mice exposed to an anxiety-related environment was observed." (PMID 33348565, 2020). "For example, it has been reported in mice that the BDNF Met allele interacts with the E2 surge/drop during the estrous cycle, leading to increased anxiety and impaired cognitive performance." (PMID 30356121, 2020). "Variation in the gene coding for brain-derived neurotrophic factor (BDNF) has been associated with estrogen-dependent hippocampal function, anxiety, and sex differences both in human and experimental models." (PMID 30356121, 2020). "Administration of GPS also produced an increase in BDNF mRNA levels in the hippocampus associated with LPS-induced anxiety-like symptoms in experimental rats." (PMID 30460112, 2018). "More specifically, our findings shed light on the role of the BDNF Val66Met polymorphism in the development of anxiety-related traits in mixed race adolescents in the context of childhood adversity." (PMID 29805780, 2018). "BDNF expression was found to be reduced in the hippocampus and cortex of germ-free mice, and reduced expression of BDNF was found to be specifically associated with increased anxiety and progressive cognitive dysfunction." (PMID 30441866, 2018). "Polymorphisms in the BDNF gene are associated with an increased risk of psychiatric disorders like bipolar disorder, anxiety, and eating disorders." (PMID 30510522, 2018). "We also investigated the levels of BDNF, an important factor associated with the pathogenesis of anxiety-like behaviors." (PMID 30460112, 2018). "Chronic fluoxetine treatment also increased neurogenesis, with an upregulation of BDNF in the medial habenula and medial hypothalamus that are also considered as anxiety-associated brain regions." (PMID 29099059, 2017).
Anxiety (continued). "It should be noted that Val66Met in the BDNF gene has been associated with episodic memory performance and anxiety/neuroticism." (PMID 29387021, 2017). "CAPS2 promotes BDNF secretion, and its mutation is associated with autism and anxiety-like behavior." (PMID 28122057, 2017). "Data are also scarce to assess the behavioral changes as a function of BDNF expression, but the downregulation of BDNF seems to be associated with increased anxiety-like symptoms." (PMID 28620285, 2017). "NCS-1 deficiency also results in decreased levels of BDNF (present data) and causes anxiety and depressive-like behavior." (PMID 28122057, 2017). "Current evidence suggests that individuals with the BDNF Val66Met polymorphism (Rs6265), which includes 25% of the population, are at an increased risk of developing either an anxiety or depressive-related disorder." (PMID 28287464, 2017). "Among adults, BDNF methylation levels in blood or saliva are associated with anxiety, major depressive disorder, post-traumatic stress disorder, and a history of childhood maltreatment or exposure to domestic violence." (PMID 28680507, 2017). "The use of several animal models have also implicated BDNF in anxiety-like behaviors and have shown a decreased BDNF expression in response to different types of stressors." (PMID 27267954, 2016). "We combined several factors that are consistently associated with increased risk of AN—adolescent females, genetic predisposition to anxiety imposed by the BDNF-Val66Met gene variant, social isolation stress and caloric restriction (CR)." (PMID 27045846, 2016). "On the other hand in rodents, overexpression of the TrkB high affinity receptor for BDNF, leads to increased anxiety indicating that BDNF signalling is associated with anxiety." (PMID 26539329, 2015). "Consistent with the existing literature, the present study found that maternal BDNF methylation was associated with maternal anxiety levels and also with childhood exposure to domestic violence." (PMID 26649946, 2015). "Consistent with the existing literature, the present study found that maternal BDNF methylation was associated with higher levels of maternal anxiety and greater childhood exposure to domestic violence." (PMID 26649946, 2015). "Further, increased latency was observed in the light/dark exploration test in BDNF deficient mice, indicating that the deletion of brain BDNF induces both obesity and anxiety." (PMID 25309465, 2014). "In humans, polymorphism in the BDNF gene has been associated with anxiety-related behaviors and a reduction in the hippocampus volume, especially in individuals exposed to early life stress." (PMID 24690945, 2014). "Animal models with BDNF Met allele exhibited increased anxiety-related behaviors under stress, and this phenomenon implicates an effect of the gene (BDNF genotype) × environment (stress) interaction on the mood." (PMID 25383981, 2014). "On the same track, Pandey and colleagues have demonstrated that BDNF deficiency induced anxiety in rats, followed by increased consumption of alcohol." (PMID 26501066, 2014). "In a cross-sectional study of a healthy population, plasma BDNF levels were negatively associated with somatization, obsessive–compulsiveness, interpersonal sensitivity, and anxiety." (PMID 23785661, 2013). "In line with these clinical findings, animal study showed that a variant BDNF mouse (BDNF Met/Met) reproduced the phenotypic hallmarks of humans with this variant allele, and exhibited increased anxiety-related behaviors." (PMID 23968401, 2013). "Similar anxiety-related behavioral phenotypes have also been observed among mice and humans having the p.Val66Met variant in BDNF." (PMID 24109560, 2013). "This said, in animals, systemic BDNF treatment reduced signs of anxiety in several behavioral tests coincident with increased hippocampal neurogenesis, suggesting a causal role for peripheral BDNF in promoting behavioral changes." (PMID 23824678, 2013).
Anxiety (continued). "Taken together, these studies suggest that reduced BDNF–Arc signaling and synaptic plasticity contribute to both dysphoria associated with a genetic vulnerability for anxiety and to anxiety induced by environmental stressors, such as alcohol withdrawal." (PMID 23584115, 2012). "A deficiency of mature BDNF and its receptor TrkB has been implicated in increased anxiety-related behavior and decreased neuronal complexity of hippocampal neurons." (PMID 22529971, 2012). "The studies found that compared with NP rats, P rats expressed lower levels of BDNF and Arc and had lower dendritic spine density in the CeA and MeA and that these characteristics were associated with high innate anxiety-like behaviors." (PMID 23584115, 2012). "Growing evidence has linked growth of dendrites and spines in the BLA – caused either by stress or BDNF overexpression – to enhanced anxiety-like behavior." (PMID 22272355, 2012). "The action of BDNF has been linked to molecules important for the control of brain energy metabolism and anxiety-like behaviors such as neuropeptide Y (NPY) and glucocorticoid receptor (GR)." (PMID 22163304, 2011). "In contrast, simultaneous ablation of BDNF and SERT alleles exacerbates anxiety in double knockout mice and reduceshippocampal serotonin levels, confirming an important functional interplay between BDNF and serotonin in the brain." (PMID 17502911, 2007). "Stimulatory effect of perinatal mirtazapine on BDNF expression in the offspring of the stressed dams might be linked with increased 5-HT neurotransmission and with decreased anxiety." (PMID 40855004, 2026). "In this sense, although the reduction of BDNF, mTOR pathway activation has been associated to an increased anxiety-like behavior, other hippocampal neural markers might be correlated with the lower anxiety elicited by female MMP-9 OE mice." (PMID 40405318, 2025). "Notably, cross-species genetic homology has been identified in critical pathways - such as polymorphisms in the brain-derived neurotrophic factor (BDNF) gene - that modulate anxiety-like behavioral profiles under stress in both mice and humans." (PMID 40635883, 2025). "However, having more anxiety was associated with a 87.8% posterior probability of more BDNF at the end of winter (β = 0.72, CI95%[-0.48, 1.96], pd = 87.8%, ps = 84.5%)." (PMID 41164095, 2025). "Numerous studies demonstrated the association between BDNF and anxiety." (PMID 39937424, 2025). "Notably, we found that individuals with higher baseline cognitive function and lower anxiety symptomatology (i.e., characteristics associated with higher initial BDNF levels) experienced the most pronounced seasonal decline." (PMID 41164095, 2025). "Given the established influence of sex, brain-derived neurotrophic factor variants, personality traits and anxiety levels on nicotine use, this study aimed to conduct a comprehensive association analysis of these factors within a cohort of women who use nicotine." (PMID 40806241, 2025). "Given the hippocampus’s crucial role in mood regulation, it is plausible that the BDNF Val66Met polymorphism may influence behaviour and anxiety." (PMID 40806241, 2025). "Similarly, anxiety-related behaviors have been linked to the downregulation of BDNF and pAkt in female mice." (PMID 41141866, 2025). "Here, we investigate how astrocytic BDNF modulates anxiety susceptibility." (PMID 40777598, 2025). "And the genetic variants related to anxiety, such as the 5-HT transporter gene and the brain-derived neurotrophic factor gene, may further heighten SI by influencing brain neuroplasticity and emotional regulation." (PMID 40624464, 2025). "Additionally, the Met/Met genotype of BDNF rs6265 has been linked to decreased plasma BDNF levels and heightened anxiety in panic disorder, as well as more severe cancer‐related neuropathic pain in survivors." (PMID 40222813, 2025).
Anxiety (continued). "BDNF promotes neuroplasticity, especially in brain regions closely linked to emotion regulation, such as the prefrontal cortex and hippocampus, thereby alleviating anxiety." (PMID 41144483, 2025). "BDNF is a key molecule for learning and memory as it is involved in neurogenesis and synaptic plasticity, and it also plays an important role in reducing behaviours associated with anxiety." (PMID 38808523, 2024). "It has been suggested that women carrying the BDNF Met allele may be more sensitive to the potential impact of reproductive hormones on anxiety and depressive disorders." (PMID 38732283, 2024). "We then assessed CeA expression of stress-related genes, including CRF (Crh), CRF1 receptor (Crhr1), Fkbp5, brain-derived neurotrophic factor (Bdnf), and nuclear receptor subfamily 3 group C member 1 (Nr3c1; which encodes the GR), which are known to modulate anxiety and alcohol drinking." (PMID 38509197, 2024). "The underlying mechanisms for the increased anxiety profile in hypothyroidism are likely multifactorial but may be attributed in part to decreased BDNF levels and an imbalance in the oxidant–antioxidant system in the brain." (PMID 38988101, 2024). "Interestingly, all mice are able to recover from the anxiety-like phenotype in the long term, except the male heterozygous mice carrying the Val66Met variant of BDNF." (PMID 38785785, 2024). "The results of this study provide further evidence that personality traits, anxiety and the rs6265 polymorphism of the BDNF gene may be risk factors for susceptibility to addiction to psychoactive substances." (PMID 38255861, 2024). "Indeed, some evidence also suggests a link between BDNF polymorphisms and an increased risk for anxiety and attention deficit hyperactivity disorder (ADHD)." (PMID 39194714, 2024). "Interestingly, lower anxiety in the predator stress model was linked to increased brain-derived neurotrophic factor expression and hippocampal peroxidation, indicating potential damage in this brain region." (PMID 39275174, 2024). "The BDNF gene Val66Met (rs6265) single nucleotide polymorphism (SNP) is a genetic variant which has been widely researched for its association with susceptibility to anxiety in mice." (PMID 38672038, 2024). "Even the association between peripheral BDNF and state anxiety could predict changes in somatic symptoms after treatment with escitalopram in patients with panic disorder." (PMID 39408702, 2024). "This human BDNF Val66Met SNP has been linked to psychiatric diseases, including anxiety." (PMID 39569070, 2024). "Within these nominally significant overlapping pathways, some have been previously associated with pain problems and/or anxiety symptoms (e.g., the brain derived neurotrophic factor signaling pathway (GO:0031547); the glucocorticoid receptor signaling pathway (GO:0042921)." (PMID 37146008, 2023). "Reduced BDNF and increased corticosterone are associated with increased anxiety." (PMID 38001850, 2023). "Human BDNF Val66Met polymorphism has been linked to human psychiatric diseases including anxiety." (PMID 37205980, 2023). "We hypothesized that an increased level of anxiety in SM would be associated with reduced concentrations of BDNF and impaired DA metabolism in the hippocampus." (PMID 36498900, 2022). "Likewise, the level of anxious preoccupation among gastric cancer patients appeared higher among carriers of the rare Met allele of the SNP in BDNF (rs6265), suggesting an association between anxiety and this SNP in gastric cancer patients." (PMID 35528795, 2022). "Furthermore, BDNF deficiency due to anxiety-related behaviour in mice increases aggressive tendencies and anxiety levels in the open field and elevated-plus maze assays." (PMID 35628418, 2022). "The reduced expression of BDNF in the hippocampal dentate region causes anxiety-like behaviour." (PMID 36422338, 2022).